SETDB1 (SET domain bifurcated histone lysine methyltransferase 1)
Diseases named in the same sentence as SETDB1 in open-access papers (continued):
Sharing a sentence is not in itself a finding about the gene and the disease.
cancer (continued). "A recent screen in several human AML cancer cell lines has identified up-regulated SETDB1 to secure silencing of retrotransposons, thereby attenuating an anti-cancer immune and interferon response." (PMID 34174884, 2021). "SETDB1 knockdown in HCC cell lines exhibited downregulation of T-lymphoma invasion and metastasis gene (Tiam1), reducing cancer migration and suggesting the positive correlation between SETDB1 and Tiam1 in HCC." (PMID 33255318, 2020). "An increasing volume of evidence suggests that SETDB1 plays a role in the tumorigenesis of various cancers, classifying SETDB1 as an oncoprotein." (PMID 33343623, 2020). "These include well-known cancer-associated genes, such as CCND1 (25 tumors), CDK4 (25 tumors), MDM2 (23 tumors), SETDB1 (23 tumors), ERBB3 (11 tumors), ERBB2 (11 tumors), MYC (10 tumors) and MYCN (five tumors)." (PMID 32025003, 2020). "An increasing volume of recent evidence supports that SETDB1 plays a crucial role in the tumorigenesis of various cancers, validating the classification of SETDB1 as an oncoprotein." (PMID 33343623, 2020). "We observed a correlation between the SETDB1 copy number and the SETDB1 expression level in both types of cancer (p < 2.4 × 10–40)." (PMID 33343623, 2020). "We found that the overexpression of SETDB1 in HNC metastatic lines plays a significant role in cancer development." (PMID 31768101, 2019). "SETDB1 expression was evaluated in primary and metastatic cell line pairs of HNC by qRT-PCR and western blotting because dysregulation of SETDB1 is critical for different signaling pathways and has been suspected to stimulate cancer phenotypes." (PMID 31768101, 2019). "Overexpressed in several cancer phenotypes SETDB1 is necessary for the survival of over 70% of tested AML cell lines." (PMID 31428579, 2019). "This, therefore, highlights the potential use for combination therapy of AKT inhibitors, as well as histone methyltransferases such as SETDB1, to potentially investigate the heterogenic events occurring in cancer development." (PMID 31405032, 2019). "The main H3K9 KMTs, namely, G9A, GLP, SUV39H and SETDB1, are deregulated in many cancers, and variations in the global or local patterns of H3K9 methylations are found in tumor cells." (PMID 31398867, 2019). "Emerging evidence supports that SETDB1 functions as an oncogene in many cancers that include sporadic cutaneous melanoma, liver cancer, and colorectal cancer." (PMID 31245293, 2019). "The mRNA and protein expressions of SETDB1 in HCC tissues were significantly lower compared with the para-carcinoma normal tissues (p < 0.001), and the expression of SETDB1 in HCC cells was also lower compared with the normal liver cells (p < 0.001)." (PMID 30503969, 2019). "Over the past few years, SETDB1 has been widely considered as an oncogene playing a critical role in many human cancers." (PMID 30309377, 2018). "We found that the expression of SETDB1 correlated well with the grade of tumorigenesis with later-stage cancer expressing higher level of SETDB1." (PMID 26471002, 2015). "To further confirm these results, we generated stable cancer cell lines expressing inducible short hairpin RNAs (shRNAs) against SETDB1." (PMID 26471002, 2015). "Comprehensive epigenomic and transcriptional profiling to understand how SETDB1 regulates gene expression in cancer cells warrants future study." (PMID 26471002, 2015).
cancer (continued). "The cancer driver signatures for SETDB1, YEATS4, NSD3, and BRD4 in TCGA datasets suggests that these genes are important cancer therapeutic targets and potential patient tailoring markers for epigenetics drug discovery efforts." (PMID 24874471, 2014). "While SETDB1 has been validated as a cancer driver in several disease types, NSD3/WHSC1L1 has not been widely investigated for its role in oncogenesis and tumor progression." (PMID 24874471, 2014). "Future work could explore the extent to which QLXP modulates SETDB1 activity and its downstream effects on gene expression in the context of gastric mucosal inflammation and cancer." (PMID 40143211, 2025). "Because the interaction with Atf7IP is critical for Setdb1-mediated silencing of retrotransposons, disrupting this interaction may be an attractive strategy to reduce immune evasion of cancers." (PMID 40339988, 2025). "Beyond its established roles in cancer progression and proliferation, SETDB1 has recently been recognized as a key regulator of immune cell differentiation and function by affecting processes, such as B and T lymphocyte development, cytokine production, and activation of innate immune genes." (PMID 39764697, 2025). "By addressing these issues, developing selective SETDB1 inhibitors could provide new avenues for effective cancer treatments with minimal adverse effects." (PMID 39764697, 2025). "Indeed, Setdb1 has several cytosolic substrates and binding partners that are important for normal cellular processes and the development of cancer." (PMID 40339988, 2025). "These multifaceted roles make SETDB1 an attractive epigenetic target for novel cancer therapies." (PMID 39764697, 2025). "Setdb1 and Atf7IP interact through coiled-coils, and targeting this 1:2 complex with peptides or compounds that block Setdb1/Atf7IP binding could open new areas for cancer treatment." (PMID 40339988, 2025). "SETDB1, a key epigenetic regulator, has emerged as a promising target in cancer treatment due to its role in silencing genes through H3K9me3 modifications and promoting oncogenic signaling through non‐histone protein methylation, contributing to tumor proliferation and resistance." (PMID 39764697, 2025). "SETDB1-dependent methylation either augments or impedes the respective kinase activities in the regulation of proliferation, differentiation, and cell fate, as well as repression of cancer." (PMID 38520019, 2024). "Previous studies have shown that abnormally high levels of SETDB1 stimulate the proliferation, migration, and invasion of tumor cells in various cancers, including breast cancer, colorectal cancer, gastric cancer, ovarian cancer, prostate cancer, and lung cancer." (PMID 39768193, 2024). "Increased expression of SETDB1 is found in several drug-resistant cancer cells." (PMID 39703687, 2024). "In addition, transposable factors and immune clusters have been found to be silenced by SETDB1-dependent H3K9 methylation in cancer, suggesting that SETDB1 is a negative regulator of tumor intrinsic immunity." (PMID 39583200, 2024). "The relationships between SETDB1 expression and TILs in different types of cancer were exhibited." (PMID 39768193, 2024). "In conclusion, our results reveal that SETDB1 could predict the prognosis of cancer patients and correlate with immune infiltration levels in HCC." (PMID 39768193, 2024). "SETDB1 is one of such enzymes that exhibits aberrant activity in cancer cells." (PMID 39133578, 2024). "Furthermore, a pan-cancer analysis indicated that SETDB1 is overexpressed in the majority of cancers, suggesting its oncogenic character." (PMID 39519018, 2024).
cancer (continued). "Since SETDB1 is known for its repressive action on gene expression, we made the hypothesis that SETDB1 could repress TGFβ inhibitors as already described in the cancer context." (PMID 38691608, 2024). "It would be also valuable to evaluate whether SETDB1 inhibition would sensitize other cell lines that are resistant to DOX-induced cytotoxicity, especially in cancer cell lines harboring SETDB1 amplification." (PMID 37970920, 2023). "SETDB1 expression is frequently upregulated in various cancers." (PMID 37850636, 2023). "Besides, several methyltransferases like SMYD3, EZH2, and SETDB1 are also abnormally expressed in common human cancer lines." (PMID 37220590, 2023). "Notably, researchers have found that inhibition of SETDB1 can make immunotherapy more effective for patients, and the protein is essential for the study of new anti‐cancer drugs." (PMID 37220590, 2023). "Experiments from the current study showed that SETDB1 loss in hypoxia hyperactivates immune-inflammatory responses by increasing TE-derived dsRNAs, suggesting that combination of immune checkpoint blockade and SETDB1 inactivation is more efficacious for cancer cells with hypoxic TME." (PMID 37850636, 2023). "Therefore, we assessed the DNA methylation levels of SETDB1 and its prognosis value in various human cancers." (PMID 35656340, 2022). "It is not fully understood to what extent SETDB1’s role in cancer development can be attributed to its ability to repress the expression of TEs, but SETDB1 loss has been shown to result in TE activation and loss of cellular fitness driven by a viral mimicry response in some cancers." (PMID 35602594, 2022). "Recent studies reported that targeting epigenetic mechanisms in cancer cells, including DNA methylation by DNMTs, histone methylation, and demethylation by SETDB1, LSD1, and KDM5B could derepress ERVs transcription and lead to induction of interferon response." (PMID 36323669, 2022). "SETDB1, a potential candidate to predict prognosis, has been well-studied in cancer cells." (PMID 35159180, 2022). "This study was aimed at investigating the oncogenic role of SETDB1 in human cancers." (PMID 35656340, 2022). "The expression of SETDB1 is highly correlated with cell proliferation in cancer cells." (PMID 35159180, 2022). "For example, activated AKT kinase is beneficial for cancer cell proliferation and survival, while SETDB1 could activate AKT by mediating methylation of AKT K64 residue and promote the development of non-small-cell lung carcinoma (NSCLC)." (PMID 36582533, 2022). "Besides, SETDB1 has been shown to allow cell escape from the immune-mediated control and proliferate in cancers of breast, liver, and prostate." (PMID 35497876, 2022). "The abnormal expression of SETDB1 predicts poor prognosis, as showed by various cancer research." (PMID 35159180, 2022). "In summary, SETDB1 is considered an oncogene in multiple malignant tumours." (PMID 36582533, 2022). "Additionally, the expression of SUV39H and SETDB1 in salivary gland malignancies should be of value for potential application of targeted treatment in patients with these cancers." (PMID 36064736, 2022). "The Gene Ontology (GO) and Kyoto Encyclopedia of Genes and Genomes (KEGG) analyses also indicated that SETDB1 may function as crucial regulator in carcinogenesis of human cancers." (PMID 35656340, 2022). "Therefore, SETDB1 targeting is an attractive strategy for cancer therapy, particularly in combination with immunotherapy and radiotherapy, because of its regulatory effects on ERVs." (PMID 36582533, 2022). "Besides EZH2, typical epigenetic modification enzymes and cancer-promoting factors, SETDB1, G9A, and SETD1A, were inhibited." (PMID 34595169, 2021). "In these cancers, SETDB1 may suppress the promoter region of tumour-suppressive genes by exerting excessive H3K9 trimethylation." (PMID 34299035, 2021).
cancer (continued). "Another mechanism of SETDB1 involvement in cancer is the suppression of tumor-intrinsic immunogenicity and evasion of the immune response through inhibition of genome regions enriched with transposable elements that would trigger the host’s immune responses if activated." (PMID 34440561, 2021). "First, a deeper understanding of the enzyme’s intracellular effects and affected genes is needed since there is evidence that SETDB1 may also act as a tumor suppressor in some stages of cancer development." (PMID 34440561, 2021). "miRNA-29 contributes to the modulation of several genes, such as the upregulation of SET domain bifurcated 1 (SETDB1), an H3K9-specific histone methyltransferase, which is significantly associated with HCC disease progression, cancer aggressiveness, and poorer prognosis." (PMID 33540837, 2021). "SETDB1 depletion restores the transcriptional status of affected genes back to normal, allowing for cell re-differentiation and cancer cell transformation to normal-like post-miotic cells, especially when combined with cytotoxic drugs such as 5-fluorouracil, oxaliplatin and irinotecan." (PMID 34440561, 2021). "Further research on the use of SETDB1 inhibitors to combat aggressive cancer subtypes could help maximize the effects of current therapeutic regimens." (PMID 34440561, 2021). "The regulation of immunity through the control of TE expression is an emerging research field in cancer, and SETDB1 has been in the spotlight as the key regulator for suppressing innate immunity by limiting the overall abundance of TE transcripts in cancer cells." (PMID 33343623, 2020). "SETDB1 can promote the development of tumors by inducing H3K9me3 modification at promoters of some genes and has been demonstrated abnormally expressed in various human cancer conditions." (PMID 32393761, 2020). "SETDB1 serves as an exemplar of the difficulties faced when developing therapies that not only specifically target cancer cells but also the more elusive and aggressive stem cells that contribute to metastasis via epithelial-to-mesenchymal transition and confer resistance to therapies." (PMID 31405032, 2019). "Importantly, the silencing of SETDB1 was shown to inhibit cell proliferation, cell invasion, tumor growth and metastasis in different types of cancer." (PMID 31398867, 2019). "DZNep is a well-known inhibitor of the H3K27me3 histone methyltransferase EZH2 but its treatment also negatively regulates SETDB1 by downregulating its expression in various cancer cells lines, a mechanism that is also employed by the inhibitor mithramycin A and paclitaxel." (PMID 31405032, 2019). "The knockdown of SETDB1 increased the apoptosis rate in various cancer types." (PMID 31768101, 2019). "Cancer cells in proliferative phases are largely heterogeneous and have varying needs for different cancer types, which could explain the differences in SETDB1 and SETDB2 expression for the progression of different cancers." (PMID 30850015, 2019). "With the increased activity of SETDB1, the excess trimethylation of various tumor suppressors may block gene expression, inducing cancer invasion and metastasis." (PMID 31768101, 2019). "The gene expression level of SETDB1 was reduced in knockdown cancer cells." (PMID 31768101, 2019). "This implicates SETDB1 as a potential target for cancer vaccines, as inducing CD4+ T cells could support the expansion of CD8+ T cells in the tumor." (PMID 31405032, 2019). "Although some nonspecific inhibitors block the function of the SETDB1 protein, there is no specific agent effective yet, so the study of the role of SETDB1 and its molecular interactions in various cancers can help improve the therapeutic targeting of SETDB1 in the clinic." (PMID 31768101, 2019). "The effect of SETDB1 knockdown may be different according to the type of cancer and may play a more critical role in the cancer’s progression." (PMID 31768101, 2019).
cancer (continued). "SETDB1 is a histone methyltransferase and a role for the protein has been proposed in cancer." (PMID 26471002, 2015). "Furthermore, SetDB1 depletion using RNAi approaches in cancer cell lines or mouse xenograft models leads to a decrease in proliferation." (PMID 26405197, 2015). "Finally, we discuss how these data open new avenues to explore SetDB1 as a therapeutic target in cancers having perturbed heterochromatin regions." (PMID 26405197, 2015). "It remains to be elucidated whether the function of the MCAF1/SETDB1 complex in PML bodies is separable from that in heterochromatin in cancer cells." (PMID 23935871, 2013). "Elevated H3K9me3 levels have two implications in cancer: an increase in H3K9me3 levels in specific promoters is strongly associated with the suppression of tumor suppressor gene expression, and therefore inhibition of SUV39H1 or SETDB1 has been proposed as a promising therapeutic strategy in HCC." (PMID 40175344, 2025). "Setdb1 and Atf7IP interact through coiled-coils and targeting this 1:2 complex with peptides or compounds that block Setdb1/Atf7IP binding could be open new areas for cancer treatment [cit]." (PMID 39764026, 2024). "The expression of innate immune-related genes and antiviral response genes is upregulated in patients with hypoxic tumors and low SETDB1 expression, suggesting that targeting SETDB1 to derepress TE-related innate immune responses may be a viable strategy for eliminating hypoxic cancer cells." (PMID 39394462, 2024). "In addition, SETDB1-dependent ERV inhibition has also been shown to be associated with the regulation of CD4+ T cell differentiation and the evasion recognition by the immune system of cancer cells." (PMID 39583200, 2024). "However, the relationship between MCT1 K473 tri‐methylation and SETDB1 in cancer promotion is currently unknown." (PMID 37541664, 2023). "Thus, using colony-forming assays, we investigated whether SETDB1 ablation affects cancer cell proliferation in hypoxia." (PMID 37850636, 2023). "However, since a substantial amount of SETDB1 can be found in the cytoplasm, we looked for cytoplasmic activity of SETDB1 that may also promote cancer formation and progression." (PMID 36330589, 2022). "Furthermore, we used the online databases to explore the correlation between SETDB1 expression and immune cell infiltration level in human cancer and found that tumor-related immune cells significantly increased in tumor tissues with high SETDB1 expression levels." (PMID 35656340, 2022). "Therefore, development of a specific inhibitor against SETDB1 may serve as a promising agent for targeting Akt-driven human cancers." (PMID 36180910, 2022). "Similarly, they found that SETDB1 knockout in human cancer cells induced TE-encoded MHC-I peptide but not viral mimicry." (PMID 34294683, 2021). "SETDB1 might impact the cancer phenotype by acting on different substrates." (PMID 31398867, 2019). "We then asked whether SETDB1 overexpression drives cancer cell growth." (PMID 26471002, 2015). "The findings that SETDB1 plays a critical role in tumorigenesis and cancer progression, particularly in immune evasion and resistance to ICB therapies, place SETDB1 as a promising target for anti‐tumor therapies." (PMID 39764697, 2025). "A unique feature of SETDB1 is its tandem Tudor domains (TTD), which recognize methylated lysines on histone H3, making it a promising target for cancer therapy." (PMID 39764697, 2025). "SETDB1, which silences tumor suppressor genes and activate oncogenic AKT signaling, is overexpressed in various cancers." (PMID 39764697, 2025). "At present, there are few studies on the use of SETDB1 inhibitors to inhibit HCC progression, so we summarized SETDB1 inhibitors for other cancer therapies." (PMID 39583200, 2024).